CGAS (cyclic GMP-AMP synthase)
Diseases named in the same sentence as CGAS in open-access papers (continued):
Sharing a sentence is not in itself a finding about the gene and the disease.
tumor (continued). "Taken together, these results demonstrated that CKIP‐1 silencing could function anti‐tumour effect on OSCC cells partially via TFAM/cGAS‐STING signalling axis." (PMID 39169452, 2024). "It is well accepted that cancer cells are not only the major component of tumor, but also are often constitutively rich in cytoplasmic dsDNA, which further increases upon DNA damaging therapies such as chemotherapy to directly activate cGAS to produce cGAMP50." (PMID 38177099, 2024). "Together, these results show that the 6 Gy + INDO combination treatment restored tumor immune surveillance against aggressive 4T1 tumors, which involved at least in part enhanced antitumor innate and adaptive immune responses through cGAS/STING/type I IFN signaling." (PMID 38912586, 2024). "However, studies have reported that tumor-derived DNA, after recognition by DCs, is sensed by cGAS-STING and activates DCs to secrete the cytokine IFN-β." (PMID 39334927, 2024). "Besides, it is important to note that the dichotomous roles of cGAS-STING in tumor immunity and development are cell and context - dependent." (PMID 38510490, 2024). "Moreover, indirect inhibition of PRMT1, as well as targeting the PTM of cGAS, can be combined with each other or with immune checkpoint blockade for effective strategy to enhance the anti-tumor immunity of cancer cells." (PMID 40018367, 2024). "In addition to its antiviral role in innate immunity, the cGAS-STING pathway is increasingly recognized as a pivotal player in regulating tumor development." (PMID 38566036, 2024). "In addition, the researchers observed that pre-treated tumor cells released more cGAMP, a secondary signaling molecule of cGAS, and that cells in the co-culture system released more immune-associated proteins such as IL-2, TNF-α, IFN-γ, CXCL10, and CXCL11." (PMID 39482784, 2024). "Furthermore, a series of studies have highlighted that the cGAS-STING signaling pathway promotes tumor growth." (PMID 38817608, 2024). "Tumor-derived DNA activates the cGAS-STING pathway, instigating type I interferon (IFN) production." (PMID 39170700, 2024). "Activated cGAS-STING pathway plays a vital role in anti-tumor immunity via T cell priming." (PMID 38177099, 2024). "Moreover, Cdc2‐like kinase 1 (CLK1) is critical for residual tumor cell survival after treatment with cGAS inhibitors, and CLK1 suppression enhances sensitivity to cGAS inhibitors." (PMID 38145335, 2024). "Moreover, cGAS-STING scores were higher in cases with higher tumor grades (i.e., NPI2, NPI3, G2, and G3 subgroups) in the METABRIC cohort (P < 0.001)." (PMID 38167507, 2024). "Furthermore, the chronic activation of the cGAS-STING pathway can induce an immunosuppressive tumor microenvironment." (PMID 39105849, 2024). "An alternative application of Se nanoparticles has been in conjunction with manganese in a biosynthetic MnSe nanobomb, which proved to effectively induce ROS production and the anti-tumor immune response through the cGAS-STING signaling pathways, causing leukocytes to infiltrate the tumor site." (PMID 39408290, 2024). "In addition, they demonstrated that the cGAS-STING-dependent cytoplasmic DNA sensing pathway is required for a radiation-activated adaptive anti-tumor immune response." (PMID 38347787, 2024). "In addition to its functions in immune cells, the activation of the cGAS-STING signaling pathway in tumor cells has been shown to induce anti-tumor immune responses in several studies." (PMID 38970078, 2024). "Therefore, pharmacological inhibition of PRMT1 is an effective strategy to activate cGAS and enhance anti-tumor immunity." (PMID 40018367, 2024). "If PTEN displays antitumor activity, in part through the stimulation of type I IFN response, its loss might disrupt the cGAS-STING pathway and contribute to the immunosuppressive microenvironment of GBM tumours." (PMID 38214828, 2024).
tumor (continued). "However, further investigations regarding the regulation of cGAS–STING expression in tumor cells, particularly in dMMR GC, are needed." (PMID 39242811, 2024). "Taken together, the results may indicate that activation of cGAS-STING pathway is sufficient to initiate the anti-tumor immune response and to modulate the TME of “cold” tumors with initially high levels of STING protein." (PMID 38832958, 2024). "Therefore, this study develops a powerful sensitizer of radio-immunotherapy and uncovers some differences between EBRT and RNT in the activation of cGAS-STING pathway-related anti-tumor immunity." (PMID 38831378, 2024). "Furthermore, cGAS-knockdown in MKN45 cells decreased subcutaneous tumor volume and growth rate in BALB/c-nude mice." (PMID 39050748, 2024). "However, in human clinical trials, targeting cGAS-STING pathway results in insufficient or unsustainable anti-tumor response." (PMID 38832958, 2024). "Further in vivo and in vitro analyses reveal that zebularine stimulates cGAS-STING-NF-κB/IFNβ signaling to enhance tumor cell immunogenicity and upregulate antigen processing and presentation machinery (AgPPM), which promotes effective CD4+ and CD8+ T cell-mediated killing of tumor cells." (PMID 38755254, 2024). "BANF1 impedes the anti-tumor immune response by inhibiting the cGAS-STING pathway." (PMID 39867908, 2024). "Thus, the cGAS-STING signaling pathway has the potential to counteract the inhibitory effects exerted by tumor cells on interferons, by continuously releasing substantial amounts of interferons." (PMID 39063990, 2024). "In this regard, MRE11 may play stage-dependent roles, by limiting tumor initiation through cGAS activation and immunosurveillance and promoting tumor progression and chemoresistance by enhancing DNA damage repair." (PMID 39872378, 2024). "The cGAS-STING pathway not only mediates protective immune defense against various DNA-containing pathogens but also detects tumor-derived DNA to generate intrinsic anti-tumor immunity." (PMID 39445027, 2024). "cGAS-STING pathway plays an important role in tumor immunity and development." (PMID 38510490, 2024). "Moreover, silencing PFKP collaborated with RT to restrain tumor cell survival, stimulated cGAS/STING signaling pathway and increased cell apoptosis." (PMID 38977778, 2024). "In this review, we cover the current understanding of how radiation therapy, which uses ionizing radiation to kill cancer cells, mediates an anti-tumor immune response through the cGAS-STING pathway, and how STING agonists might potentiate this." (PMID 38659582, 2024). "Treated with cGAMP or STINGa could reverse the inactivation of type I IFN signaling in resistant tumor cells, illustrating that the function of cGAS was broken." (PMID 38993569, 2024). "Moreover, our study also demonstrates that tumor exosomal ENPP1 can hydrolyze endogenous 2′3′‐cGAMP produced by cells to inhibit cGAS‐STING pathway in bystander cells." (PMID 38498770, 2024). "Furthermore, this type of cGAS/STING activation is linked to chronic NF-κB activation, driven by chromosomal instability-induced tumour cell-intrinsic micronuclei containing dsDNA." (PMID 39403376, 2024). "Of note, the activation of cGAS-STING pathway may exert a direct anti-tumorigenic effect on tumor, a potential effect that needs to be clarified by the future study." (PMID 38773213, 2024). "Also, cGAS-STING scores are correlated with genomic instability metrics, such as homologous recombination deficiency (P < 0.001) and tumor mutational burden (P < 0.01)." (PMID 38167507, 2024). "Tumor cells undergoing ICD secrete type I IFNs through the activation of TLR3 by cyclic guanosine monophosphate-adenosine monophosphate synthase/stimulator of interferon genes (cGAS/STING) signaling pathway." (PMID 39916954, 2024). "However, it remains largely elusive how tumor-intrinsic cGAS signaling is suppressed to facilitate tumorigenesis by escaping immune surveillance." (PMID 37193698, 2023).
tumor (continued). "However, this places greater demands on the understanding of the temporal and spatial mechanisms involved in the tumor-promoting or inhibitory effects of cGAS-STING, as well as on the ability to correctly localize this pathway." (PMID 37965570, 2023). "Thus, the active regulation of cGAS-STING signaling events is expected to develop novel therapeutics against tumor and infections." (PMID 37153576, 2023). "Hence, MIC-mediated tumor immunity or TIME relies on active cGAS/STING signaling from its pathogenesis to antitumor effects of different chemotherapies, ICIs, and radiotherapies." (PMID 37380989, 2023). "When cGAS senses tumor-derived double-stranded DNA, it activates STING by producing cGAMP." (PMID 36980689, 2023). "Recent evidence suggests that cGAS-STING signaling may also be involved in the promotion of tumor proliferation and metastasis." (PMID 37965570, 2023). "Furthermore, the cGAS-STING signalling pathway induces an anti-tumour immune response by sensing the DNA damage response (DDR) and stimulating the innate immune response within tumours." (PMID 37448962, 2023). "DNA-containing EVs from anti-tumor topotecan (DNA topoisomerase I inhibitor)-treated breast cancer cells activate the cytokine release of dendritic cells by cGAS-STING signaling activation in cytosolic DNA-mediated innate immune responses, leading to a more robust anti-tumor immune response." (PMID 37823055, 2023). "In tumor cells, genomic instability may lead to accumulation of cytosolic DNA that induces cGAS-dependent cGAMP production leading to tumor-intrinsic STING activation." (PMID 36394642, 2023). "During this process, hypermethylation might occur in several genes especially MLH1 but not STING, resulting in the generation of MSI-H cancers with high expression of cGAS-STING in tumor cells concomitant with immune cell activation in the TME." (PMID 37345163, 2023). "Furthermore, other studies have demonstrated that not only tumor-derived DNA but also the immunostimulatory second messenger cGAMP released by tumor cells can activate the cGAS-STING pathway." (PMID 38203626, 2023). "Regarding other renal cell carcinomas, high STING mRNA levels and high immunohistochemical cytoplasmic expression of STING have been reported in renal medullary renal cell carcinoma, supporting further studies assessing the role of the cGAS-STING pathway in the immunotherapy of this tumor." (PMID 37120444, 2023). "The PARP inhibitor olaparib induces CD8+ T cell infiltration and activation in vivo through activation of the cGAS/STING pathway in tumor cells with paracrine activation of dendritic cells and was more significant in HR-deficient than in HR-proficient breast cancer cells." (PMID 37174127, 2023). "In patients with brain metastases treated with SRS, overzealous activation of cGAS-STING may similarly effectuate the development of a pro-inflammatory tumor microenvironment and damage normal tissues." (PMID 37173897, 2023). "Similarly, the number of apoptotic tumor cells in the TYST‐sh‐cGAS+GPC3‐CD8+ T group was significantly less than those in the TYST‐GPC3‐CD8+ T group (p < 0.0001)." (PMID 37986544, 2023). "In human TNBC, tumors with high GAS and low STING were associated with fewer tumor-infiltrating lymphocytes and were linked to decreased distant metastasis-free survival (DMFS), whereas tumors with low cGAS and high STING had characteristics associated with a more favorable prognosis." (PMID 38139802, 2023). "Therefore, ZnFe2O4‐PTX@CCM programmatically initiated and enhanced cGAS/STING pathway in tumour cells, followed by promoting DCs maturation, increasing immune cells infiltration, and remodelling the immunosuppressive TME." (PMID 38264691, 2023). "In addition to the innate immunity-promoting action of cGAS, also recruitment of cytolytic CD8 T cells in the tumor microenvironment has been shown to be very dependent on cGAS activity." (PMID 36960066, 2023).
tumor (continued). "In addition, activation of cGAS by Mn2+ can also alarm the immune system to inhibit cancer development by promoting tumor cell senescence and cytokine production." (PMID 36926351, 2023). "Our paradigm also recognizes a subset of patients who might instead benefit from inhibition of cGAS–STING signalling to curb tumour-intrinsic chronic inflammation and its immune-suppressive sequalae (cGAShighSTINGlow)." (PMID 37612508, 2023). "Together, these data suggest that cGAS silencing may inhibit the infiltration of adoptive transferred CTLs into the tumor environment to trigger tumor cell apoptosis." (PMID 37986544, 2023). "The CRISPR/Cas9 system down-regulates the methionine transporter SLC43A2 and restricts the methionine uptake by tumor cells, thereby relieving the methionine competition pressure of T cells; simultaneously, the released nutrition metal ions activate the cGAS/STING pathway." (PMID 37532731, 2023). "The primary DNA sensor that triggers the innate immune response is cGAS, a protein found throughout the cell that plays crucial roles in anti-tumour immunity, autophagy, cellular senescence, defence against microbial infection, and autoimmune and inflammatory diseases." (PMID 37448962, 2023). "Many studies have indicated that activation of cGAS by self-DNA could improve anti-tumor immunity by enhancing tumor immune surveillance, accelerating cellular senescence, and promoting apoptosis." (PMID 37834184, 2023). "However, some reports suggest that cancer cells with elevated cGAS/STING/IRF3 protein levels in tumor progression and metastasis exhibit enhanced cGAS-STING pathway activation, which induces mitochondrial outer membrane permeability and triggers apoptosis." (PMID 37354378, 2023). "However, DNA-damaging cancer therapies can support both local and distant tumor immunogenicity through activation of the cGAS/STING/IFN-1 pathway in tumor cells." (PMID 37834346, 2023). "Moreover, the expression of unstable DNA intermediates in MMRd tumor cells activates cGAS-cGAMP-STING signaling inducing the production of type I interferons, IL-6 and TNF." (PMID 37492581, 2023). "Many previous findings suggest that the cGAS-STING pathway-mediated innate immune regulation is the most important aspect affecting tumor survival, not only in its anti-tumor role but also in shaping the immunosuppressive tumor microenvironment (TME) through a variety of pathways." (PMID 37965570, 2023). "Thus, the cGAS/STING pathway represent a very attractive opportunity to increase anti-tumor immunity and cancer cell adjuvanticity." (PMID 37180110, 2023). "While a lot remains to be known regarding the mechanisms underlying cGAS-STING–mediated immunosurveillance of mitotic errors and their respective implications for tumor evolution, defective micronuclei are now well established as potential hubs for chromothripsis." (PMID 37017932, 2023). "Interestingly, the non-canonical NF-κB pathway in dendritic cells (DCs) has been shown to interfere with the anti-tumor activity of cGAS-STING during radiotherapy." (PMID 38139802, 2023). "In addition, we observed that poorly differentiated tumor cells exhibited higher levels of cGAS expression in contrast to well-differentiated tumor cells in pMMR CRCs." (PMID 37345163, 2023). "Although numerous human STING agonists have been developed and entered clinical trials, the efficacy of STING agonist monotherapy is poor, highlighting the need to conduct more in-depth research on the mechanism of the cGAS-STING pathway in the tumor environment." (PMID 37153627, 2023). "For instance, the cGAS-STING-mediated IFN-I response and the IFN-I-associated senescence could promote tumour initiation by producing various protumourigenic cytokines." (PMID 37448962, 2023). "These released Mn2+ could significantly activate cGAS and increase the activity of the related proteins of cGAS-STING signaling to further amplify the anti-tumor immunity of tumor-associated macrophages (TAM)." (PMID 37153576, 2023).
tumor (continued). "However, in tumor cells that have adjusted to significant chromosomal instability, particularly in relapsed, treatment-resistant cancers, the cGAS–STING pathway often supports cancer progression, fostering the epithelial-to-mesenchymal transition (EMT)." (PMID 38139802, 2023). "However, in tumor development and antiviral infections, the cGAS-STING pathway plays a role in preventing disease development." (PMID 37600809, 2023). "In addition to pathogen recognition, cGAS-STING signalling is also important for tumour immunity because it induces type I IFN expression and activates innate and adaptive immunity." (PMID 37667220, 2023). "Therefore, understanding the contexts that influence complex pathways such as cGAS-STING either in promoting or countering tumor progression is a formidable task." (PMID 38139802, 2023). "Since certain types of DNA damage can lead to mitotic blockage and mitotic cell death, cGAS may also affect other types of anti-tumor responses that use DNA damage as a mechanism of action." (PMID 37965570, 2023). "Given that persistent chronic inflammation in chromosomally unstable tumors can foster tumor development, it has been discovered that cGAS-STING signaling inactivation can selectively inhibit the survival of chromosomally unstable (CIN) triple-negative breast cancer cells." (PMID 37920470, 2023). "Because the cGAS/STING pathway is essential for anti-tumor immunity, we further determined whether PRMT1 is a rational target for immunotherapy." (PMID 37193698, 2023). "Both tumor cells and myeloid cells express cGAS/STING, but accumulating evidence suggests that cGAMP is primarily produced by tumor cells and released as an immunotransmitter to activate STING in myeloid cells and stimulate antitumor immunity by triggering Type I IFN production." (PMID 36757811, 2023). "Vacant Tumor microparticle induces macrophage conversion to M2 type via cGAS/STING/TBK1/STAT6 pathway, promoting M2 type macrophage proliferation and M1 type macrophage apoptosis, and M2 type macrophages, in turn, promote TRC proliferation, leading to tumor growth and metastasis." (PMID 35861052, 2023). "Tumor-derived DNA leads to the activation of the cGAS–STING pathway." (PMID 38239354, 2023). "Hence, NPPDT‐56MESS + L not only kills cancer cells by ROS and 56MESS, but also effectively activates the cGAS‐STING pathway to elicit anti‐tumor immunity, representing a combined chemotherapy and immunotherapy strategy for the treatment of UM." (PMID 37807827, 2023). "However, tumor-derived DNA that remains undegraded can activate the cGAS-STING pathway, induce type I IFNs, and drive immune cell recruitment." (PMID 37153627, 2023). "A recent study found that medicinal plant-derived mitochondrial DNA remolded TAMs for reprogramming anti-cancer immunity and facilitating tumor eradication by inducing the cyclic GMP-AMP synthase/stimulator of interferon genes (cGAS/STING) pathway via nanovesicles." (PMID 38022518, 2023). "In addition to cell-intrinsic DNA sensing in tumor cells, the cGAS-STING pathway can be activated in immune cells within the TME by tumor-derived DNA via membranous vesicles, such as exosomes, which fuse with immune cell membrane." (PMID 38203626, 2023). "Its inhibition represents a synthetic lethal approach to blocking tumor growth while concurrently activating the cGAS-STING signaling pathway to enhance tumor immune infiltration, highlighting what we believe to be a new role for POLQ in the tumor immune environment." (PMID 36976649, 2023). "Moreover, therapies that disrupt DNA damage repair to elevate cytosolic DNA levels, such as PARP inhibitor, CHK1 inhibitor, and ATM inhibitor, synergize with anti-tumor immunotherapy in part through activating the cGAS/STING pathway." (PMID 37193698, 2023).